TYR (tyrosinase)
Diseases named in the same sentence as TYR in open-access papers (continued):
Sharing a sentence is not in itself a finding about the gene and the disease.
melanoma (continued). "Additional pigmentation-related genes associated with melanoma risk are tyrosinase (TYR); tyrosinase-related protein 1 (TYRP1); solute carrier family 45, member 2 (SLC45A2); and solute carrier family 24, member 4 (SLC24A4)." (PMID 24392023, 2013). "The canine melanoma vaccine, fully licensed in 2010 after conditional licensing in 2007, encodes human tyrosinase, allowing the immune system to break tolerance to canine tyrosinase and generate an effective immune response against tumor cells." (PMID 24204366, 2013). "In this way, the Tyr phenoxide present in the G-site of GST would be able to abstract one of the acidic methylene protons linked to the sulfone moiety, releasing the tyrosinase-activated melanoma prodrugs." (PMID 24300447, 2013). "The aim of this study was to determine the presence and the intensity of humoral immunity to melanoma-associated antigens: melanin and tyrosinase in patients with melanoma, in people with vitiligo and in control healthy people." (PMID 22834951, 2012). "Serum tyrosinase activity or positive tyrosinase RT-PCR in melanoma patients has been shown to be correlated with higher risk of relapse, but only 55% of these patients will experience a clinical relapse." (PMID 22287956, 2012). "The aim of this study was to determine the presence and the intensity of humoral immunity to melanoma-associated antigens: tyrosinase and melanin, in patients with melanoma, in persons with vitiligo and in control healthy people." (PMID 22834951, 2012). "Briefly, a cocktail of 5 melanoma-associated synthetic peptides (gp100, tyrosinase, MAGE-A2, MAGE-A3 and MART-1 or MAGE-A1) restricted to HLA-A2 or A24 and KLH were used for DC pulsing." (PMID 22895835, 2012). "A role for GM-CSF DNA as an adjuvant was established in a phase I/II trial using a DNA vaccine encoding for hgp100 and tyrosinase epitopes resulting in specific CD8+ responses in 42% of the treated melanoma patients." (PMID 21197271, 2010). "The most commonly used markers are the melanoma/melanocyte tissue-differentiation antigens, including tyrosinase and melanoma-associated antigen recognized by T cells (MART-1)." (PMID 20163701, 2010). "Isolated and expanded mRNA was analyzed for the presence of melanoma-associated tumor antigens gp100, tyrosinase or MART1." (PMID 16911798, 2006). "After pulsing with a cocktail of 5 melanoma-associated synthetic peptides (gp100, tyrosinase, MAGE-2, MAGE-3 and MART-1 or MAGE-1) restricted to HLA-A2 or A24 and KLH, cells were cryopreserved until used." (PMID 15676080, 2005). "In conclusion, RT–PCR tyrosinase mRNA expression is a reliable and reproducible marker associated with a high risk of melanoma progression and we encourage its clinical use in routine follow-up." (PMID 14562017, 2003). "The tyrosinase expression was related with the clinical course, in an attempt to ascertain if the finding of circulating melanoma cells is associated with a higher relapse rate and/or shorter DFS." (PMID 14562017, 2003). "Tyrosinase hyperactivity can cause skin issues like age spots and melanomas." (PMID 41191233, 2025). "SLC24A5 transports calcium or potassium ions into the melanosome and plays a role in melanogenesis, while SLC45A2 is a sodium–hydrogen exchanger of melanosomes, regulating tyrosinase activity in human melanocyte; both genes have been proposed as risk factors for melanoma development." (PMID 40869905, 2025). "Besides hyperpigmentation caused by overexpressed or overactivated TYR, another common disease associated with dysfunctional TYR is melanoma, which is characterized by excessive melanin synthesis catalyzed using TYR." (PMID 40651969, 2025). "Furthermore, dysfunctional tyrosinase can result in the formation of abnormal melanin, which can damage DNA and elevate the risk of melanoma-inducing mutations." (PMID 40332760, 2025).
melanoma (continued). "Another complex candidate is ECI-006, which carries a combination of three mRNAs for dendritic cell (DC) activating molecules such as CD40L, CD70 and caTLR4 (TriMix), and several mRNAs encoding for melanoma TAAs such as tyrosinase, gp100, MAGE-A3, MAGE-C2, and PRAME." (PMID 39081320, 2024). "Non-cancer skin diseases (e.g., hyper-/hypo-pigmentation disorders linked to impaired melanin biosynthesis and tyrosinase activity), as well as malignant pathologies (e.g., melanoma), constitute promising research directions with cannabinoids, as recently reviewed by several authors." (PMID 37242431, 2023). "To evaluate the effects of HLCE on melanogenesis at the molecular level, we measured the expression of key melanogenic genes, including Microphthalmia-associated transcription factor (MITF) and TYR in B16F1 melanoma cells using quantitative reverse transcription (qRT)-PCR." (PMID 38068559, 2023). "Mutations in TYR can result in the production of abnormal proteins and increase melanoma risk." (PMID 35646893, 2022). "We found that one SNP, rs1042602, in the pigmentary locus TYR, could be associated with melanoma susceptibility and prognosis." (PMID 36556369, 2022). "The possible explanation behind the association of rs1042602 and melanoma risk could be explained if we consider that a less active tyrosinase could lead to a light-skin phenotype and consequently to a “melanoma risk phenotype”." (PMID 36556369, 2022). "However, the upregulation of tyrosinase activity and excessive accumulation of melanin would cause skin disorders and related diseases, such as freckles, malignant melanoma, and Parkinson’s disease." (PMID 36590855, 2022). "In 2015, BioNTech initiated a multicenter, open-label, dose-escalation phase I trial (Lipo-MERIT, NCT02410733) to assess the efficiency and safety of FixVac (BNT111), which is composed of RNA-LPX encoding NY-ESO-1, MAGE-A3, TPTE, and tyrosinase, for the treatment of advanced melanoma patients." (PMID 34696168, 2021). "TYR encodes one of the most studied melanin enzymes that plays a crucial role in the early steps of melanin synthesis and has been detected in 100% of investigated human melanomas in some studies." (PMID 34422947, 2021). "In addition, when melanoma cells over-expressing ΔNp73 were injected into mice, they developed depigmented tumors due to loss of active tyrosinase, which reactivates the EMT signaling cascade, a mesenchymal-like cell phenotype, and increased invasiveness." (PMID 34680379, 2021). "Moreover, low TYR expression in BRAF-mutated melanoma subtypes showed a significant association with longer survival." (PMID 34199192, 2021). "For example, halistanol trisulphate, a C-29 steroidal detergent isolated from the Indo-Pacific sponge Haliclona sp., was shown to inhibit the maturation of tyrosinase to a form that is associated with melanin synthesis in the pigmented human melanoma cell line, MM418." (PMID 32486036, 2020). "For patients with malignant melanoma, the presence in blood of mRNA encoding for tyrosinase, MAGE-3 (melanoma-associated antigen 3), MCAM (melanoma cell adhesion molecule), p97 (transitional endoplasmic reticulum ATPase) and HMBS (hydroxymethylbilane synthase) is typical." (PMID 31572192, 2019). "The application of tyrosinase was further extended in the molting process of insects.The abnormal accumulation of melanogenesis products may cause cancer (melanoma), age spots, freckle and other dermatological problems." (PMID 28777326, 2017). "Our findings show that inhibition of Hsp90 and BRAF signaling in human melanoma cells is, as expected, associated with induction of cell differentiation that leads to increased cell pigmentation characterised by increased tyrosinase protein expression and melanin content." (PMID 28811486, 2017).
melanoma (continued). "The patient is a carrier of two common variants in TYR gene, p.Ser192Tyr and p.Arg402Gln of which only the variant p.Arg402Gln was associated with increased risk for melanoma in one large population study with odds ratio (OR) 1,21, but not in two other similar studies." (PMID 28720148, 2017). "The biological interaction between HLA-A and TYR shows an apparent inverse relationship between susceptibility to GV versus malignant melanoma, suggesting that GV may result from dysregulation of normal processes of immune surveillance against melanoma." (PMID 26870082, 2016). "Mechanistic studies revealed that Lunasin treatment of isolated melanoma CICs induced expression of the melanocyte-associated differentiation markers Tyrosinase and Microphthalmia-associated Transcription Factor concomitant with reduced expression of the stemness factor NANOG." (PMID 27566591, 2016). "Additionally, cells of a melanoma clone (wild type for tyrosinase, C/C) implanted into BALB/c nu/nu mice (homozygous mutation for albino tyrosinase, c/c) developed massive pulmonary metastases a few weeks later." (PMID 27657058, 2016). "Immunotherapy may be involved in the treatment because tumor cells express tumor-associated antigens, for example, MART1, gp100 and tyrosinase in melanoma." (PMID 25801067, 2015). "As males and females differ in their circulating levels of sex hormones, it is feasible that hormones impact ion exchange or tyrosinase activity in a way that modifies the effect of these variants on melanoma risk, perhaps through alterations to melanogenesis or skin pigmentation." (PMID 25789475, 2015). "Moreover, studies from our laboratory have shown that the pharmacological inhibition of tyrosinase resulted in depigmentation of melanoma cells and a concomitant increased susceptibility to hypericin-PDT." (PMID 25076130, 2014). "Variants in TYR, including SNPs correlated with our lead SNP, have previously shown strong association with skin, hair and eye colour, tanning ability, vitiligo and melanoma risk via GWAS." (PMID 23326517, 2013). "In addition, in 2010 the USDA approved the canine melanoma vaccine, OnceptTM, a DNA vaccine encoding human tyrosinase, on the basis of clinical trials demonstrating improved overall survival of dogs with melanoma treated with this vaccine." (PMID 24764533, 2013). "We found that tumor lesions expressed melanoma associated antigens (MAA) tyrosinase, tyrosinase related protein (TRP)-1, TRP-2 and gp100, which could be applied as targets for the immunotherapy." (PMID 24213320, 2012). "Interestingly, TYR has previously been associated with melanoma in GWAS studies performed in Caucasian populations other than our South European sample." (PMID 21559390, 2011). "As other active derivatives of the compound cause an increase in protein glycosylation in B16 melanoma cells, the authors hypothesize that the test compound inhibited tyrosinase by modifying the sugar moieties of the enzyme." (PMID 19865532, 2009). "The ability of the CTLs to recognize the processed peptides derived from the cellular genes, such as those encoding MART-1 or tyrosinase in melanoma, led to the recognition that protective immune responses are often directed towards tumor-associated, rather than tumor-specific, antigens." (PMID 18533025, 2008). "Interestingly, the TYR allele that confers risk for vitiligo is protective against melanoma, suggesting that strong anti-tyrosinase expression protects vitiligo patients against melanoma." (PMID 39421737, 2024). "We demonstrate that targeted deletion of Cxcr2 in tyrosinase-expressing melanoma precursor cells concurrent with induction of the BrafV600E transgene and loss of Pten expression or induction of NRasQ61R and loss of Ink4a, resulted in a significant reduction of melanoma burden." (PMID 37270599, 2023). "However, whether the increased activity of tyrosinase is the direct cause of the transformation into melanoma is unclear." (PMID 35204163, 2022).
melanoma (continued). "Thus, tyrosinase expression is limited only to melanocytic tumors such as most melanomas, desmoplastic melanoma (a relatively uncommon variant of melanoma), pigmented neurofibromas, or melanoma metastatic tumors to other organs." (PMID 33260768, 2020). "We found that PE and PCA significantly suppressed melanin content and cellular tyrosinase activity through a decrease in the expression of melanogenic enzymes and microphthalmia-associated transcription factor (Mitf) in α-melanocyte stimulating hormone-stimulated mouse melanoma cells." (PMID 28825660, 2017). "The hypothesis is that chimpanzee adenovirus (ChAd) targeted by anti-CD40 camelid single-domain antibody (sdAb) containing a human tyrosinase (huTyr) cassette (a melanoma xeno-antigen) will cause maturation of myeloid DC, elaboration of the xeno-antigen payload, and an anti-tumor immune response." (PMID 27558513, 2016). "In a clinical study, twenty-seven, grey, melanoma-bearing, horses were assigned to three groups (n = 9) and vaccinated on days 1, 22, and 78 with DNA vectors encoding for equine (eq) IL-12 and IL-18 alone or in combination with either human glycoprotein (hgp) 100 or human tyrosinase (htyr)." (PMID 25967290, 2015). "In mouse melanoma cells, DHC treatment significantly downregulated the melanogenesis-related genes: Microphthalmia-associated Transcription Factor (MITF), tyrosinase (TYR), and Tyrosinase-related protein 1 (TRP1) compared with the α-MSH control (p < 0.05)." (PMID 41596671, 2026). "The selective activation of novel triazenes in murine and human melanoma cells through a tyrosinase-responsive promoiety is discussed." (PMID 41976146, 2026). "In vitro, 5 mg/mL PCOPs reduced hydrogen peroxide (H2O2)-induced fibroblast senescence by 39.66% and significantly (p < 0.05) reduced tyrosinase activity and melanin synthesis in melanoma cells (B16)." (PMID 41683092, 2026). "4-Hydroxycinnamoyl-malate (4-HCM), a water-soluble constituent of C. junos callus, was evaluated for its effects on skin pigmentation by assessing anti-tyrosinase activity and melanogenesis in melanoma cells." (PMID 41596305, 2026). "In vitro assays demonstrated PFSO's significant efficacy in reducing the melanin content and tyrosinase activity in α-MSH-stimulated B16F10 murine melanoma cells." (PMID 41976540, 2026). "The inhibition of key enzymes in skin aging, such as tyrosinase, hyaluronidase, and collagenase, was evaluated, as well as cytotoxicity in keratinocytes and human melanoma cells." (PMID 41511974, 2026). "NOX4 generates reactive oxygen species that have been found to reduce melanin formation in mouse melanoma cells, possibly by inhibiting the synthesis of tyrosinase." (PMID 41183498, 2026). "Eight (10%) patients were identified that carried pathogenic mutations in known melanoma predisposition genes POT1, MITF, OCA2, SLC45A2 and TYR." (PMID 39315505, 2025). "This strategy offered a promising therapeutic approach and provided the basis for conducting the first trial of xenogeneic DNA vaccination in canine malignant melanoma using the human tyrosinase (hTyr) gene." (PMID 40284831, 2025). "For CD63 and PMEL, the GO term GO:0006583 (melanin biosynthetic process) and its associated genes TYR and DCT were positively associated, suggesting activation of the tyrosine-to-melanin conversion pathway in the Melanoma-A region." (PMID 41279463, 2025). "Preclinical and clinical studies have shown that xenogeneic DNA vaccination with tyrosinase gene family members can produce immune responses against melanoma, resulting in tumor rejection or protection and prolongation of survival." (PMID 40284831, 2025).
melanoma (continued). "Most previous reports have focused on curcumin or other derivatives, whereas systematic investigations into THC’s role in modulating tyrosinase activity, melanin content, and ROS levels in melanoma cells are limited." (PMID 41446503, 2025). "Variants in TYR, TYRP1, CDKN2A, and HERC2 significantly contributed to risk, and light brown eye and hair colors were strongly associated with increased melanoma risk." (PMID 40429816, 2025). "Nonetheless, it is clear that tyrosinase function and Pten gene dosage both influence the probability of melanoma initiation in Braf CA/+ and Braf CA/+PtenΔ/+ mice." (PMID 40571713, 2025). "After treatment with substance P, an undecapeptide, the melanin content and tyrosinase activity were significantly downregulated in B16F10 mouse melanoma cells." (PMID 40672371, 2025). "As only a limited number of compounds exhibit tyrosinase-dependent cytotoxicity in B16BL6 melanoma cells, we employed a strategy to enhance the sensitivity of this cell line to o-quinone metabolites." (PMID 39858507, 2025). "Pyrazole derivatives are promising candidates for tyrosinase inhibition, particularly in melanoma anticancer therapy." (PMID 40332760, 2025). "Nanoencapsulation of quercetin prolongs and enhances its antitumor activity in melanoma models, but many other tumors underexpress tyrosinase and cannot activate the prodrug." (PMID 40867327, 2025). "Two well established models for identifying potential skin-whitening agents have been used to assess the anti-melanogenic effects of Allium species, the mushroom tyrosinase and the murine melanoma B16 cell line." (PMID 40508310, 2025). "Our findings indicate that THC significantly inhibits the expression of tyrosinase activity in melanoma cells." (PMID 41446503, 2025). "We specifically investigated how THC influences melanin production and tyrosinase activity, a key enzyme in the melanogenesis pathway, in A375 melanoma cells." (PMID 41446503, 2025). "This triggers the transcription of apoptotic genes, elevating ROS levels and leading to endoplasmic reticulum stress-mediated apoptosis, particularly in highly tyrosinase-expressing cells such as those in melanoma." (PMID 40732270, 2025). "Herein, to explore the potential of TYR as a catalyst to activate anti-cancer prodrugs against melanoma drug resistance, we designed a clickable prodrug approach in which drugs will be only toxic against melanoma cells after TYR catalysis." (PMID 40651969, 2025). "Tyrosinase inhibition therapy with both natural compounds and synthetic therapeutics have yielded promising effects in melanoma cells." (PMID 40332760, 2025). "SPEF treatment effectively inhibited α-MSH-induced melanin overproduction and intracellular tyrosinase activity in B16F10 melanoma cells." (PMID 40003988, 2025). "Since B16BL6 melanoma cells in that study were insufficiently sensitive to tyrosinase metabolites, we knocked down the cytoprotective regulator NRF2 to enhance sensitivity." (PMID 39858507, 2025). "Melanoma cells typically express elevated levels of tyrosinase, which not only contributes to skin pigmentation but also plays a role in cell survival and proliferation." (PMID 40332760, 2025). "Tyrosinase inhibitors act as functional antagonists of the tyrosinase enzyme, which regulates the rate of melanin synthesis, leading to reduced melanin production in melanoma cells and potentially limiting tumor growth." (PMID 41157098, 2025). "The developed nanocapsules demonstrated prolonged quercetin release, increased bioavailability, and inhibited tumour growth in both 2D and 3D models of melanoma, showing their potential for application in high tyrosinase-expressing tumours." (PMID 40732270, 2025). "(2011) used the L-DOPA oxidation rate to determine the cellular tyrosinase activity in the G361 melanoma cell line exposed to UVA rays." (PMID 40040652, 2025).